IL10 (interleukin 10)
Diseases named in the same sentence as IL10 in open-access papers (continued):
Sharing a sentence is not in itself a finding about the gene and the disease.
tumor (continued). "Notably, ABR-238901, a small molecule that inhibits the interaction of S100A9 with its receptors, decreases the secretion of IL-6 and IL-10 from MDSCs, inhibits the neoangiogenic process, but would not have shown satisfactory efficacy in reducing tumour progression." (PMID 34445745, 2021). "Notably, tumor-infiltrating lymphocytes (TILs) isolated from act-A-treated mice secreted higher levels of the typical effector cytokines IFN-γ and TNF-α and lower levels of the immunosuppressive cytokine IL-10 upon ex vivo antigenic stimulation compared to untreated mice." (PMID 34548096, 2021). "One hypothesis is that IL-10 stimulates NK activity under certain conditions, which allows for cancer cell destruction and tumour regression; however, this tumour regression may not be replicable in humans due to species-specific differences in IL-10 or other related immune pathways." (PMID 34944729, 2021). "Further, IL-10 treatment could not stimulate the expression of Fc receptors on NXS2 tumor cells." (PMID 33912464, 2021). "The general activation of NK cells upon coculture with tumor cells may also partially explain the minimal, non-significant differences in secretion levels observed for some cytokines (e.g., IL-10, sFas-L, and granzyme B) upon comparison of MOCK and CAR-expressing NK-92 cells." (PMID 34804035, 2021). "To determine whether the IL-10+Ad-hTERT combination therapy induced memory antitumor CD8+ T cell responses, we selected the combination therapy-cured mice, and rechallenged them through injection of respective tumor cell lines in contrary side to the first inoculation." (PMID 33717103, 2021). "Macrophage polarization may be reprogrammed to tumor cell killing by treatment with tyrosine kinase inhibitors sunitinib and sorafenib, or fenretinide [4-hydroxy (phenyl) retinamide], which inhibit STAT3 or STAT6 in macrophages, thereby blocking IL-10 secretion." (PMID 34831167, 2021). "In addition, tumor cells can decrease the expression of CD80/CD86 molecules to block the activation of T cells and increase the expression of B7-H1 and B7-H4 molecules to intensify the secretion of IL-10 and induce apoptosis in TILs through upregulation of Fas/FasL signaling in T cells." (PMID 34885122, 2021). "Briefly, mTOR could regulate the expression of cytokines/chemokines, including interleukin-10 (IL-10) and transforming growth factor-β (TGF-β), and/or membrane receptors, such as cytotoxic T-Lymphocyte protein 4 (CTLA-4), PD-L1 and PD-1, to modulate tumor immune cells." (PMID 34458019, 2021). "We also observed a rapid decrease CSF IL-10 in several days after corticosteroid administration in our clinical practice; while IL-10 levels may sometimes decrease to the normal range, no change in the tumor is observed on computed tomography (CT) scan." (PMID 33618687, 2021). "Given the capacity of YY1lo NKT cells found in other tissues to produce IL-10, we hypothesized that YY1lo NKT cells would secrete IL-10 in tumors, but at least at the time point tested, which was ~12 days after tumor implantation, the cells did not express IL-10." (PMID 32127556, 2020). "Moreover, Tn antigen on tumor cells interact with macrophage galactose-specific lection (MGL) on antigen-presenting cells, driving an immune inhibitory signaling by increasing anti-inflammatory interleukin-10 (IL-10) production and inducing effector T cell apoptosis." (PMID 33260328, 2020). "Similarly, FREE and IL10 pathways (both involving pro-inflammatory cytokines connected to NF-κB pathway) were enriched in lymph node positive vs. negative tumors in a distant metastasis positive tumor subgroup (M1: N1 vs. N0 comparison)." (PMID 32947901, 2020). "It is becoming clear that IL-10 serves as a non-redundant suppressive mechanism of MDSCs, and accordingly, blockade of IL-10 signaling or neutralization of IL-10 leads to alleviated T-cell suppression, delayed tumor progression, and improved therapeutic efficacy." (PMID 32793192, 2020).
tumor (continued). "Moreover, TGF-β and IL-10 can impair the cross-presentation of DCs to T cells in multiple cancers and it has been shown that the suppression of TGF-β and IL-10 receptors on self-differentiated DCs enhanced the activation of effector T cells against CCA tumor cells." (PMID 32781527, 2020). "Collectively, this study suggested IL10 could inhibit the growth of the transplanted tumor in vivo and prolong survival of mice, and the primary mechanism may be the indirect inhibition of pro-inflammatory cytokines IL6 and TNF-α secretion and tumor angiogenesis formation." (PMID 32742480, 2020). "However, the survival time among the immunisation groups were similar, whether the tumour bearing mice were immunised with or without the IL-10 signalling blockade." (PMID 31277636, 2019). "We wish to investigate whether blocking IL-10 at the time of immunisation, which increases the numbers of antigen specific IFNγ CD8+ T cells, better prevent TC-1 tumour growth in mice than immunisation without IL-10 signalling blockage, especially in therapeutic setting." (PMID 31277636, 2019). "IL-10 is not a pan-inhibitory cytokine of inflammatory responses; it is known to activate and increase CD8α cytotoxic capacity which may be significant for anti-tumour responses." (PMID 30692549, 2019). "Furthermore, tumor-restraining CAF may increase antitumor immunity, by secretion of immunomodulatory cytokines such as IL-10, TNF, and IL-6, aiding in recruitment of macrophages and T lymphocytes, thus converting an immune-suppressive into immune-stimulating cancer microenvironment." (PMID 30871158, 2019). "On the other hand, these results indicate that tumor-derived oxysterols may shape the TME inducing a pro-tumor milieu, as confirmed by the detection in the TME of Mock-4T1 tumors of higher levels of the type-2 cytokine transcripts Il4, Il13, as well as the anti-inflammatory Il10 transcripts." (PMID 30333826, 2018). "However, tumour expression of IL-10 was not a prognostic factor in terms of BCSS." (PMID 29256156, 2018). "Thus, we cannot exclude the possibility that most of the suggested biomarkers of PCNSL (such as IL-6, IL-10 and CXCL-13) and soluble receptor proteins (such as sCD27 and sIL-2R) were more abundant in PCNSL patients because they had originated in PCNSL tumor tissue." (PMID 29299134, 2017). "Interestingly, tumor-infiltrating MDSC are the predominant producers of IL-10 and also depend on IL-10 to develop their immunosuppressive function in vivo further, confirming the fundamental role of IL-10 for the development and maintenance of a permissive TME." (PMID 28275576, 2017). "Thus, our findings implied that IL-10 might contribute to tumor aggressiveness in AITL rather than other subtypes." (PMID 29100307, 2017). "In addition, TAM-derived prostaglandin E2 (PGE2), IL-10, and indoleamine 2,3-dioxygenase play important roles in the induction of Tregs and TAM-derived CCL17, CCL18, and CCL22 are chemotactic factors for Tregs, which results in the suppression of T cells in the tumor microenvironment." (PMID 28241846, 2017). "This would suggest that IL10-mediated immunosuppression is similarly present in benign and malignant tumour microenvironments and while clearly contributing to impaired immune responsiveness is not a defining driving force behind tumor progression in the malignant tumour environment." (PMID 28410380, 2017). "In addition, there was virtually no coexpression of IL-17 and IL-10 observed in tumor samples." (PMID 27014625, 2016). "Indeed, MSC can interfere with the recognition of tumor cells by immune system producing and releasing immunoregulatory factors as TGFβ, prostaglandin E2 (PGE2), tumor necrosis factor α (TNFα), indolamine 2, 3-dioxygenase (IDO), hemeoxygenase (HO), NOS2, ARG1–2, IL10." (PMID 26967390, 2016).
tumor (continued). "The superiority of HOCl-oxidized whole tumor cell lysate preparation could be attributed to the induction of less Treg cells in peripheral blood and absence of serum IL-10 in the vaccinated mice and not in mice treated with other UVB-irradiated or freeze-thawed whole tumor lysate preparations." (PMID 26343191, 2015). "Based on our above observation that PD-1 was upregulated on activated T cells after being exposed to tumor cells expressing ligand PD-L1, we hypothesized that the interactions of tumor cells and activated T cells could influence the production of cytokines, such as IL-2, IFN-γ, IL-10, and TNF-α." (PMID 26361042, 2015). "Additionally, this reduction in tumor size could not be reproduced with either IL-10 or IL-2 expressing tumors alone." (PMID 26217588, 2015). "However, our finding of a predominantly low IL10 expression combined with high IFNG expression in the highly responsive cluster group B, might be consistent with a high Th1/Th2 balance, a known marker of an appropriate anti-tumor immune response." (PMID 25432519, 2014). "However, IL-4 promotes IL-10 in tumor tissue and the latter interferes with the expression of inflammatory factors, including IL-12 and IFN-γ, blocks the activation of NK cells and reduces the antigen formation of tumor cells in order to escape cytoimmunity against tumor growth." (PMID 24520300, 2014). "Importantly, BV6 significantly increased the secretion of IL-8, IL-6, granulocyte–macrophage colony-stimulating factor (GM-CSF) and monocyte chemoattractant protein-1 (MCP-1) from tumor cells into the supernatant, whereas IL-10 and VEGF remained largely unchanged (data not shown)." (PMID 25501823, 2014). "However it is not quite clear, whether IL-10 is produced by the tumour cells, by the immune cells or both." (PMID 23950929, 2013). "Thus, while tumor macrophages can efficiently take up and present antigen, the presence of IL-10 and the absence of potent costimulatory molecules such as OX40L that are present in pro-inflammatory sites limit their ability to initiate immune responses locally." (PMID 23653658, 2013). "Therefore, we suggest that the non-ATA haplotype, with a higher IL-10 mRNA expression level, may be more important in promoting tumor aggressiveness in late-stage patients than in early-stage patients." (PMID 22848356, 2012). "In this study, the authors underline that the dichotomy Th1/Th2 is not easily applicable to tumour specific T cells in humans, and that the ratio IFN-γ/IL-10 could be an indicator of responses associated to long-term survivors, rather than the delineation of clear Th1 or Th2 profiles." (PMID 23284752, 2012). "Thus, the role of IL-10 in tumor rejection is not as clear cut as previously thought and may be a double-edged sword." (PMID 22899945, 2012). "Interestingly, IL-4, IL-6, IL-10 and GM-CSF have no regulatory effects on the expression of B7-H4 on tumor cells, indicating that the expression of B7-H4 in tumor cells may be functionally distinct and differently regulated compared with APCs." (PMID 22013483, 2011). "Therefore the inhibition of tumor growth should be due to the lack of the suppressive effect that IL-10 may have on anti-tumor immune responses." (PMID 20525400, 2010). "Interestingly, unlike spleen Treg cells, tumor-associated Treg cells express IL-23R and activates STAT3 in response to IL-23, leading to upregulation of the Treg-specific transcription factor Foxp3 and the immunosuppressive cytokine IL-10." (PMID 20885915, 2010). "However, they still present tumor antigens and induce IL-10-producingCD4+/CD25+ regulatory T cells that inhibit antitumor immunity.Nevertheless, using an anti-IL-10 mAb and CpG ODN, it is possible to induce arobust antitumor CTL response and tumor rejection in vivo." (PMID 19190769, 2008). "The TME inhibits DC maturation via TGF-β, IL-10, and VEGF, skewing them towards a tolerogenic phenotype that promotes immune tolerance rather than tumor elimination." (PMID 41244711, 2025).
tumor (continued). "In the PBMC cultures, IL-10, TGF-γ, IL-6, and IL-1β cytokine levels were not detectable, suggesting that matrix alone without tumor tissue is not sufficient to induce production of these cytokines from immune cells." (PMID 40425576, 2025). "Blockade of M-MDSC-derived IL-10, but not Arg1 or iNOS, released human CRC tumour M-MDSC-mediated suppression on T cells and restored T cell proliferation." (PMID 38464388, 2024). "IL-10 weakens the response of CD8+ T cells, while TGF-β excludes T cells, including CAR-T cells, from the tumor, significantly impairing their function." (PMID 39136031, 2024). "In the tumor microenvironment, STAT3, which is predominantly activated by IL-10 and IL-21, but not by IL-6, enhances the effector function and survival of Texterm cells, thereby improving tumor regulation." (PMID 38582965, 2024). "Non-neoplastic astrocytes facilitate tumor growth, realizing anti-inflammatory cytokines such as transforming growth factor beta (TGF-β), interleukin 10 (IL-10), and granulocyte colony-stimulating factor (G-CSF), and promote expression of HIF-1a." (PMID 39768176, 2024). "IL-2 was detectable only in presence, but not in absence, of tumor cells, while TNFα was unchanged and all other cytokines (IL-6, IFN-γ, GM-CSF, IL-10) were slightly reduced without tumor cells." (PMID 38514793, 2024). "Moreover, levels of IL-10 and IL-4 decreased significantly in CMU-Pb-L5 group, indicating that L.p CMU-Pb-L5 intervention could reduce the expression of immunosuppressive cytokines in vivo, thus improving the tumor immune microenvironment and inhibiting tumor growth." (PMID 39439459, 2024). "Deletion of the polyketide synthase (pks) genotoxic island from E. coli NC101 decreased tumor multiplicity and invasion in AOM/Il10−/− mice, without altering intestinal inflammation." (PMID 39726700, 2024). "The results have shown no systemic toxicity, but a vaccine-induced anti-tumor response with increased IFN-γ, TNF-α, IL-5 and IL-10 production." (PMID 37513985, 2023). "When levels of expression for the cytokines (IL10 and TGFB) are bigger than 0.6, the M1 phenotype polarizes to an M2a macrophage which will not create a suitable environment for tumor elimination." (PMID 37283734, 2023). "In line, analysis of culture supernatants by Legendplex assays showed a significant increase in IL-2, IFNγ, IL-10 and TNF secretion after treatment with 1 nM CC-3, but not with the isotype control or when target antigen negative tumor cells were used." (PMID 37122707, 2023). "Second, the main tissues tested in this study for IHC were tumor tissues, and paraneoplastic tissues were not included to compare the differences of VEGF, IL-8, IL-10, PIK3CA, and RIP2." (PMID 36567775, 2022). "Regardless of tumor type, patients with values of sTIM3, IFNα, IFNγ, IL1β, IL1α, IL12p70, MIP1β, IL13, sCD28, sGITR, sPDL1, IL10 and TNFα below the median had longer overall survival (p<0.05)." (PMID 36405727, 2022). "These tolerogenic DCs present tumor antigen without proper costimulation (CD80/CD86), express inhibitory molecules (PDL1/CTLA4), and secrete immunosuppressive factors (TGF-β, IL-10, IL-27, NO, Arg, and IDO)." (PMID 35972798, 2022). "In line with diminished IL-4 signaling, IL-4ra-KO mice exhibited low expression levels of the alternative macrophage marker genes Arg1 and Il-10, which furthermore, were not enhanced in iWAT in the presence of the cachexigenic LLC tumor." (PMID 35210363, 2022). "Further analysis showed that the contents of IL-10 and TGF-β was significantly increased in tumor tissues, but there were no significant changes of TNF-α, IL-6, and IL-1β observed compared with the control group." (PMID 35646112, 2022). "This was also consistent with earlier reports showing that alternatively activated M2-like TAMs, which are known to harbor induced IL10 rather than induced IL12, promote tumor progression, whereas the IL12-expressing M1-type TAMs are tumoricidal." (PMID 34575998, 2021).
tumor (continued). "Protein levels of IL-10 and interferon-gamma cytokines did not significantly differ between LC–COPD and LC in either tumor or non-tumor lung specimens." (PMID 32414037, 2020). "Although the thymus was atrophied in all IL-10−/− mice (regardless of tumor status), percentages of DN2 were reduced, and DN3 and DN4 subpopulations increased, in IL-10−/− vs. control tumor-bearing animals (Figure 5B1)." (PMID 32582141, 2020). "Blocking glycolysis activities with 2-DG treatment did not significantly inhibit tumor growth, but downregulated the macrophage M1 marker iNOS and M2 marker CD206 expressions, although not IL-10." (PMID 32596169, 2020). "Since T cell stimulation can also be expected to be influenced by the presence of immunosuppressive factors, the expression of PD-L1, IDO, IL-10 and TGF-β was determined for all tumor cell lines in the presence and absence of stimulated PBMCs." (PMID 32504247, 2020). "No obvious changes in IL‐10‐producing CD19+ Tim‐1+ cells were observed in healthy young miR‐15a/16−/− mice, suggesting that this Breg subset was only induced in tumour microenvironment." (PMID 30467955, 2019). "E.G7 tumor cells cultured for 72 h in Static and SMG conditions produced less than 100 pg/ml of IL-10 and VEGF each with no substantial TGF-β detected in the culture wells (data not shown)." (PMID 31602007, 2019). "Indeed, when combining tumour local administration of caerin peptides with Ex/MPLA vaccine to TC-1 tumour bearing mice, the survival time was significantly extended compared with vaccination alone or caerin peptide treatment alone, whether IL-10 signalling is blocked or not." (PMID 31277636, 2019). "FAS also binds to FASL to activate the non-inherent apoptotic pathway, and tumor cells release transforming growth factor (TGF)-β and interleukin (IL)-10 to counterattack immune cells." (PMID 31737562, 2019). "In this study, inoculation of S180 tumour significantly increased kidney pro-inflammatory cytokine TNF-α (p < 0.01) and reduced kidney anti-inflammatory cytokine IL-10 (p < 0.05) without significant effects on liver TNF-α and IL-10 in mice." (PMID 31280667, 2019). "The results of this study showed that S180 tumor-bearing slightly increased hepatic TNF-α and decreased IL-10 levels, but no statistical difference." (PMID 29950302, 2018). "Curiously, the tumor protection induced by metformin was not altered when CD25+ cells were depleted, suggesting that CD4+Foxp3+IL-10+ T cells induced by metformin treatment do not impair the observed antitumor effect." (PMID 29899823, 2018). "Blocking interleukin 10 (IL-10) signalling at the time of immunization increases vaccine induced CTL responses and improves prevention of tumour growth in animal models compared to immunization without an IL-10 signalling blockade." (PMID 28810829, 2017). "There were no group differences in tumor protein concentrations of IFN-γ, IL-2, IL-4, IL-5, IL-10, and IL-12p70 (p > 0.05 data not shown)." (PMID 28811490, 2017). "Apoptotic tumor cell supernatant containing elevated levels of S1P was reported to selectively alter the production of TNF-α and IL-8, while IL-10 production was not altered." (PMID 28367448, 2017). "A delay in tumour growth was observed as long as anti‐IL‐10 or nor‐NOHA was administered, suggesting that BaF3‐RAE1ε MDSCs promote tumour growth in IL‐10‐ and arginase‐dependent manners." (PMID 28276625, 2017). "The negative correlations between IL-10-expressing B cells and CD4+ cytotoxic T cells were also observed in tumor-infiltrating cells." (PMID 27136203, 2016). "NK cell infusion significantly increased the expression of IL-10 and TGF-β in plasma and tumor tissue in the NB-Ehigh group, but not in the NB-Elow group." (PMID 27322426, 2016). "We further found an increase in regulatory cytokines including Il10 and Arg1, but not pro-inflammatory cytokines such as Il6, Tnfa and Il12 in DIO tumours compared with normal tumours using purified CD11b+ myeloid cells." (PMID 27708283, 2016).